AFP (alpha fetoprotein)
Diseases named in the same sentence as AFP in open-access papers (continued):
Sharing a sentence is not in itself a finding about the gene and the disease.
tumor (continued). "Tumor markers were normal with CEA 2.5 ng/ml, but high AFP 1984 ng/ml and CA19-9 3135 U/ml." (PMID 39734687, 2024). "The key laboratory values assessed during this phase include alkaline phosphatase (AP), glutamate oxaloacetate transaminase (GOT), glutamate–pyruvate transaminase (GPT), gamma-glutamyl transferase (GGT), albumin, total bilirubin, and tumor markers CA 19-9, CEA, and AFP (alpha-fetoprotein)." (PMID 39796681, 2024). "The more recent GSDI practice guideline of the American College of Medical Genetics and Genomics acknowledges that there is no effective tumor marker, since AFP and CEA levels are often normal despite HCC." (PMID 38974608, 2024). "The serum tumor marker levels showed HCG 853 mIU/ml, AFP 937.30 ng/ml, LDH 679 U/L." (PMID 38394502, 2024). "A series of key biomarkers such as alpha-fetoprotein (AFP), GP73, FARSB, and serum miR-483-5p have been identified through the years, signifying significant advances in the detection, prognosis, and management of this tumor." (PMID 39081317, 2024). "These criteria focus on the presence of hepatoid components within tumor tissues irrespective of the proportion of hepatoid components and serum AFP levels." (PMID 39186327, 2024). "An analysis of samples with and without relapse revealed striking differences in age, AFP, tumor size, NLR, ITC, histological grade, and MVI between the two groups." (PMID 38256485, 2024). "Importantly, serum K102-Env levels correlated well with advanced cancers and tumor biomarkers CA19-9 and AFP." (PMID 39850893, 2024). "They include laboratory parameters such as elevated alpha-fetoprotein (AFP) and gamma glutamyl transferase (GGT), pathologic parameters such as microscopic vascular invasion (MVI) by tumor, multiple tumor nodules and degree of tumor differentiation." (PMID 38454246, 2024). "In addition, MKI67, AFP, and ALB level, as well as the immune score, the stromal score, and the tumor purity (estimate score), also showed the similar results to those in TCGA-HCC dataset." (PMID 38374122, 2024). "Moreover, the occurrence of MVI is closely related to a patient’s tumor load, differentiation level, AFP level, and HBV activity and replication, while the presence of satellite nodules in patients with MVI is suggestive of tumor progression." (PMID 38476367, 2024). "After 3 cycles of chemotherapy, the tumor marker (AFP) returned to normal, and an MRI showed no masses in the pelvic or abdominal cavity." (PMID 39077470, 2024). "The phenomenon is believed to derive from acute AFP released from tumor cells killed by chemotherapy, rather than representing a lack of disease response." (PMID 38098239, 2024). "Serum tumour markers like CA 125, CA 15.3, AFP, and SCC are generally not significant during pregnancy, but markers like AMH, CEA, CA 19-9, and HE4 usually do not exhibit increased levels during pregnancy, making them potentially applicable." (PMID 38473031, 2024). "AFP-DCP expression patterns were categorized according to the number of positive tumor markers (AFP ≥ 20ng/mL, DCP ≥ 40mAU/mL), including double-negative, single-positive, and double-positive." (PMID 38903723, 2024). "Among the HCC patients, a negative correlation was found between the AFP level (rs = −0.21, p = 0.36), tumor grade (rs = −0.51, p = 0.03), tumor size >5 cm (rs = −0.53, p = 0.02), age greater than 70 years (rs = −0.45, p = 0.047) and the number of p-CTCs." (PMID 39791707, 2024). "Normal cells in vivo generally have no AFP receptors; therefore, using AFP as a transport carrier can target drug transport to the tumor site without damaging the normal cells." (PMID 38678117, 2024). "In the livers of certain FL mice, staining for AFP in the cytoplasm and c-Myc in the nucleus was observed only in limited areas, primarily within tumor lesions, whereas the majority of nodules were negative for the staining in both FL and KO mice." (PMID 39394459, 2024).
tumor (continued). "Univariate analysis of OS revealed significant associations between patient death and various factors, including Child-Pugh class, BCLC stage, previous surgical resection, history of TACE and ablation, tumor number, PVTT, distant metastasis, NLR, PLR, PNI, AFP, CRP, and PMI." (PMID 38698848, 2024). "We retrospectively analyzed the distribution, maximum diameter, echogenicity, and border of ultrasound images as well as clinical parameters, including sex, age, course of disease, serum amylase, tumor markers (CEA, CA125, CA153, CA199, AFP), and postoperative pathological diagnosis." (PMID 38890695, 2024). "Moreover, studies have shown that local injection of AFP CAR-T cells into tumors produce deeper, faster, and more lasting anti-tumor responses." (PMID 39136031, 2024). "It has been suggested that the neoplasm itself does not produce AFP, but the interaction between the primary mesoderm, from which it originates, and the endodermal elements from the yolk sac located in the liver is the source." (PMID 38256600, 2024). "KIF18A, with elevated mRNA expression in 216 HCC samples paired with para-carcinoma tissues measured by RT-qPCR, was found to be significantly correlated with serum AFP, tumor size, TNM stage, and portal vein tumor thrombus (PVTT), indicating the possible efficiency of KIF18A in HCC diagnosis." (PMID 38433242, 2024). "Tumor markers such as CA199, AFP, and CEA may be elevated or normal to assist in the diagnosis of CSGB, but have poor specificity." (PMID 40231011, 2024). "At the first surgery, the patient only had detectable tumor cells in the left lung (left CT images) and a low AFP of 52.6; at this time point, we did not detect CTCs." (PMID 38727682, 2024). "Tumor marker evaluation was negative preoperatively, including Alpha Fetoprotein (AFP) (1.25 ng/mL), but without beta-Human Chorionic Gonadotropin (β-HCG) in our hospital laboratory examination protocol." (PMID 39931213, 2024). "Clinically, patients with tumours ≤2 cm, AFP‐negative tumours, or those without obvious symptoms are frequently overlooked." (PMID 39428564, 2024). "Certain coagulation-related biomolecules, such as PIVKA-II, have become commonly used tumor markers in clinical practice for AFP-negative patients." (PMID 38334941, 2024). "It not only incorporates absolute AFP levels but AFP response over time, allowing for a dynamic assessment of tumour biology rather than just focusing on one absolute value." (PMID 38304238, 2024). "It was reported that significant correlations existed between serum PIVKA-II levels and HCC clinicopathological characteristics, such as tumor size and TNM stage, and the performance of PIVKA-II plus AFP for HCC identification was superior to each of these biomarkers used alone." (PMID 38902822, 2024). "Unlike currently recommended blood‐based tests such as AFP or CEA levels for monitoring tumor progression, PISIR integrates the proportions of specific immune clusters and their characteristic surface molecules prior to treatment." (PMID 39467150, 2024). "Thirdly, this study did not include other clinically reported HCC tumor markers, such as Lens culinaris agglutinin-reactive fraction of AFP, due to it not being routinely tested across all centers." (PMID 38903723, 2024). "In our study, we did not observe definite correlation between serum AFP level and tumor burden at diagnosis." (PMID 38833154, 2024). "An anti-alpha-fetoprotein (AFP) CAR-T has shown potent anti-tumor activity in vivo in mouse models, and a Phase I clinical trial has been conducted in patients with AFP+ HCC, the results of which are not yet available (NCT03349255)." (PMID 38473265, 2024). "Blood AFP levels were already elevated after 12 weeks of DEN-CCl4-treatment (283 ± 198.4 ng/ml [mean ± SD, n = 8]) in animals without tumour, indicating AFP production by chronic liver damage." (PMID 38889481, 2024). "Tumor markers CA 19‐9, CA 125, CA 15‐3, CEA, and alpha‐fetoprotein (AFP) were also unremarkable." (PMID 39224678, 2024).
tumor (continued). "However, some prognosis‐related factors such as AFP, AJCC, max tumor diameter, MVI, PVTT, tumor number, and Milan and UCSF criteria were insignificant, further suggesting that intra‐tumoral TLS was independent of those factors." (PMID 38498682, 2024). "Moreover, AFP can activate downstream signaling pathways, such as PI3K/Akt in tumor cells, promoting proliferation, survival, and migration." (PMID 38660138, 2024). "Interestingly, there were also significant correlations of CT texture parameters with the widely used tumor markers CA‐19‐9, CEA, and AFP." (PMID 39307946, 2024). "A total of 20 of the 115 patients were excluded due to no imaging evaluation (n=8) or missing tumor marker data (n=5), or no elevated baseline AFP and DCP levels (n=7)." (PMID 39726604, 2024). "TAC evaluated tumor morphology, biology, and liver function by combining TBS, AFP, and CP." (PMID 38611104, 2024). "Tumor marker examinations, including CEA, CA-125, CA19-1, and AFP, exhibit low sensitivity and specificity in determining the primary malignancy in MBD of unknown origin." (PMID 39583211, 2024). "In analyzing other previously reported factors related to recurrence and prognosis—such as tumor size, tumor number, AFP levels, and the NLR—none demonstrated statistical significance in the multivariate analysis." (PMID 39766066, 2024). "Compared to the other classifications, this rule is relatively conservative regarding selection, and although it includes AFP as a tumour marker, it is not very revolutionary regarding morphological aspects." (PMID 38473282, 2024). "Immunohistochemical analyses revealed that the tumor cells were negative for AFP, HepPar-1, CEA, GPC-3, CK19, CK20, Syn, CgA, and CD56 but positive for CK7, Vimentin, and Ki-67, with a Ki-67 expression level of approximately 45%." (PMID 39867929, 2024). "AFP promotes DC-mediated differentiation of regulatory T cells (Tregs) and dampens the function of CD8+T cells and NK cells, thus inducing an immunosuppressive environment and tumor progression." (PMID 38660138, 2024). "In addition to a routine laboratory workup, including liver function tests, the tumor markers carcinoembryonic antigen (CEA), carbohydrate antigen 19-9 (CA 19-9), and alpha-fetoprotein (AFP) should be included." (PMID 38398130, 2024). "The multivariable logistic analysis showed that AFP ≥ 200ng/mL, NLR ≥ 1.8, PNI ≥ 46.5, larger tumor diameter, and tumor margin non-smooth were independent risk factors for MVI (all P < 0.05)." (PMID 39090609, 2024). "However, only approximately a third of these HCC mice injected with iRGD showed a higher increase of the blood AFP level than all the HCC mice injected with PBS, complicating the investigation of iRGD-induced tumour-blood transport in this HCC mouse model." (PMID 38889481, 2024). "The lack of effect of iRGD/CendR peptide on AFP release from cultured HepG2 cells suggests that the iRGD-induced increase in the tumour-to-blood transport of AFP is not due to an increased secretion of AFP from the HCC cells into the tumour interstitium." (PMID 38889481, 2024). "They display more comprehensive ranges of tumor markers, including B-HCG and AFP." (PMID 38571873, 2024). "Similarly, alpha-fetoprotein (AFP), an HCC-specific biomarker, is considered to reflect the tumor’s biological behavior and clinical prognosis." (PMID 38053048, 2023). "Serum samples showed extremely high levels of tumor markers, such as β-HCG and AFP." (PMID 38066820, 2023). "Compared with the Metroticket 2.0 and Up-to-7 models, the AFP model was less restrictive regarding the number of tumor nodules." (PMID 36967432, 2023). "But current detection methods primarily rely upon imaging and a blood test for a non-specific tumor marker, alpha-fetoprotein, which showed inefficacy in detecting tumors smaller than one centimeter." (PMID 36915069, 2023).
tumor (continued). "The presence of a single tumor and a significant decline in AFP levels were found to be predictors of OR, while progression-free survival (PFS) directly correlated with macrovascular invasion absence, concurrent therapy, and AFP response." (PMID 36769004, 2023). "Although serum tumor markers such as CEA, CA-199, PSA, AFP, CA-125, etc., which are commonly used in clinical tumor screening tests, have been widely used, none of them can accurately and specifically predict the presence or absence of tumors." (PMID 38057833, 2023). "Finally, five variables from the stepwise selection were selected and incorporated into the final model: tumor size, tumor number, AST, ALT, and AFP threshold of 400 ng/mL." (PMID 37200967, 2023). "Immunohistochemical staining of diagnostic markers showed expression of EMA, vimentin, NSE and CD99, and absence of AFP, which is comparable to the results in the primary tumor." (PMID 38201285, 2023). "Tumor markers, namely LDH, β-hCG and AFP, may be positive depending on the nature of the components present inside the tumor." (PMID 37508611, 2023). "AFP-targeting therapies have mainly utilized chimeric antigen receptor (CAR) T-cell therapy, which involves the use of genetically modified T cells engineered to recognize target antigens expressed on tumor cells and elicit an immune response." (PMID 38173713, 2023). "This same tumor group expresses AFP, and AFP binds estrogen, but not androgen, and blocks the estrogen-driven signaling." (PMID 36834607, 2023). "Following the completion of treatment, an increase in AFP levels above age-specific reference values, even in the absence of clinical and imaging evidence of the tumor, suggests recurrence." (PMID 37686577, 2023). "In the present study, there was nodifference in the degree of necrosis in relation to the size of the largest nodule,the degree of tumor differentiation (although this was evaluated only in thepatients without total necrosis), or the AFP level." (PMID 38204906, 2023). "Furthermore, this study showed that capecitabine treatment significantly reduced Ki-67, AFP, and CEA expression levels in PDX tumor tissues, which was similar to other studies." (PMID 36742145, 2023). "In Japan, nine types of TMs are certified for use in tumor monitoring: carcinoembryonic antigen (CEA), carbohydrate antigen (CA) 199, CA125, CA50, CA724, sialyl Tn antigens (STN), alpha-fetoprotein (AFP), inhibitor of apoptosis (IAP) and tissue polypeptide antigen (TPA)." (PMID 36920593, 2023). "The TACE prognostic predictive power of the TRscore was also stable in subgroups stratified by survival status, TNM stage, AFP value, and tumor size, with high TRscore levels mainly expressed in the population who died and those with TNM stage III-IV and AFP > 300 ng/ml." (PMID 37208604, 2023). "As presented in subgroup analyses, TDF therapy showed a significantly better effect on reducing risk of HCC recurrence in patients with following tumor characteristics: Maximum diameter plus number of viable tumor ≥ 5, with MIV or MAT, AFP at LT ≥ 20 ng/ml, and well or moderate tumor grade." (PMID 36650583, 2023). "Serum alpha-fetoprotein (AFP) assessment as a tumor marker is no longer recommended as a screening tool or diagnostic method for HCC." (PMID 37868533, 2023). "The lesion might have been comprised of tumor cells that partially differentiated into ENT from AC, thereby expressing both CEA and AFP." (PMID 37027114, 2023). "The patient characteristics, such as cancer grade, inflammation, residual tumor, and AFP level, did not significantly differ between the high- and low-NQO1-expression groups, except for vascular invasion." (PMID 37695786, 2023). "To determine if IL-34 combined with AFP could improve the specificity in determining HCC, i.e., tumor size, we compared IL-34 versus tumor size, AFP vs tumor size or IL 34 + AFP versus tumor size." (PMID 35347503, 2023). "Tumour markers performed included PSA, CA-125, AFP, B-HCG, and CA 19.9." (PMID 36849651, 2023).
tumor (continued). "AFP-positive HCC patients had more female patients (P=0.048), higher proportion of HBV infection (P=0.041), lower B cell ratio (P=0.011), worse tumor Edmondson grade (P=0.001), and more microvascular invasion (P=0.049) than AFP-negative HCC patients." (PMID 36873738, 2023). "An attempt to block AFP uptake using antibodies against the AFPR was reported by Moro but it was not very effective in reducing tumor growth." (PMID 37016369, 2023). "Furthermore, the majority of patients in this study were categorized as low tumor burden (i.e., TBS ≤ 7.9 and AFP < 400 ng/mL)." (PMID 36831544, 2023). "The following factors were selected as predictive of recurrence: age, tumor number, microvascular invasion (MVI) grade, preoperative alpha‐fetoprotein (AFP), preoperative carbohydrate antigen 19-9 (CA19-9), and Eastern Cooperative Oncology Group performance score (ECOG PS)." (PMID 37689775, 2023). "Alpha-fetoprotein production of the tumor cells after LT which do not produce AFP before LT is a finding that supports the concept of intratumoral heterogeneity and tumor evolution in individual HCC nodules, which is mentioned in the literature before." (PMID 37326153, 2023). "For this patient, the levels of tumor markers, such as carbohydrate antigen (CA-125), human chorionic gonadotropin (HCG), alpha-fetoprotein (AFP), carcinoembryonic antigen (CEA), carbohydrate antigen 19 − 9 (CA19-9) and human epididymal protein-4 (HE4) were all within normal limits." (PMID 37479970, 2023). "For patients with negative AFP before surgery (i.e., AFP response = 1), the reduction of tumor size needs to exceed 33.7% using the mRECIST measurement method to achieve a pCR." (PMID 37158833, 2023). "We analyzed OS and PFS by the presence or absence of tumor number > 7, AFP value > 1900 ng/mL (median value of this cohort), BCLC stage C, MVI, EHM, and Child–Pugh class B." (PMID 36906542, 2023). "Those with EpCAM-negative and AFP-negative HCC are usually older but in earlier tumor-node-metastasis (TNM) stages." (PMID 36674932, 2023). "In striking contrast, AFP immunization combined with anti–PD-L1 treatment triggered significant inhibition of HCC progression in most liver tumor nodules, while in combination with anti-PD1, it induced slower tumor progression." (PMID 37040183, 2023). "However, the present diagnostic sensitivity of imaging and serum tumor biomarkers such as alpha-fetoprotein (AFP) is limited and cannot predict the potential for tumor metastasis." (PMID 36681851, 2023). "Patients with AFP levels < 1000 ng/mL, largest tumor size < 8 cm, and no vascular invasion had higher overall survival rates." (PMID 36967432, 2023). "Moreover, our model comprised only routinely investigated laboratory and imaging data in most HCC patients: AFP, AST, ALT, the largest tumor size, and tumor number." (PMID 37200967, 2023). "Additionally, a significant correlation was observed between AFP and tumor size or IL 34 + APF and tumor size, based on univariable analysis." (PMID 35347503, 2023). "Subgroups were divided as follows: AFP >400 ng/mL, tumor size ≤10 cm, tumor thrombus and no metastasis." (PMID 36254376, 2023). "In the training cohort, the two groups demonstrated significant differences in age, serum AFP, non-smooth tumor margins, and tumor/peritumoral liver parenchyma signal ratios." (PMID 37841420, 2023). "We assume that patients with preoperatively increased AFP have more tissue alterations resulting from previously received chemotherapy and vital nonseminomatous tumour tissue." (PMID 37490059, 2023). "In the training cohort, the following variables differed between the recurrence and no-recurrence groups: LI-RADS category, serum AFP level, maximum tumor diameter, TBIL, washout time, and TNM, BCLC, and CNLC stages." (PMID 37519810, 2023).